NORAD (non-coding RNA activated by DNA damage)
Synonyms: LINC00657
Gene: Long non-coding RNA gene on chromosome 20 (36,042,280 to 36,051,018, reverse strand). Ensembl gene ENSG00000260032.
Gene Ontology:
Molecular function: protein sequestering activity
Biological process: regulation of mRNA stability
Diseases named in the same sentence as NORAD in open-access papers:
NORAD is named in the same sentence as 68 diseases in open-access papers, as found by Europe PMC text mining. Sharing a sentence is not in itself a finding about the gene and the disease. The quoted sentences say what the papers report.
breast carcinoma (28 papers, 2016 to 2024). "The importance of NORAD in pathways linked to illnesses such as cellular senescence and breast cancer is shown by KEGG analysis." (PMID 37993524, 2023). "A study published in 2016 looking for lncRNAs as prognostic markers for human breast cancer has associated the poor overall survival (OS) with the expression levels (upregulation) of four lncRNAs, including NORAD (LINC00657) and HCG11." (PMID 33739352, 2021). "By investigating the prognostic significance of these lncRNA expressions in breast cancer subtypes, we found that an increased expression of NORAD is associated with reduced disease-free survival only in basal-like patients (P75, p = 0.002)." (PMID 33739352, 2021). "Furthermore, NORAD is reported to be a potential oncogenic gene and is associated with overall survival in breast cancer." (PMID 29121972, 2017). "When we split breast cancer patients into subtypes and evaluated the expression levels of each lncRNA, we could observe that a higher expression of NORAD was found in luminal subtypes, usually lower-risk patients, in comparison to basal-like, which have a higher risk of relapse." (PMID 33739352, 2021). "Breast cancer (BC) is the most diagnosed cancer worldwide and represents one of the malignancies in which NORAD expression is altered." (PMID 38339387, 2024). "Elevated levels of NORAD expression are detected in a series of human epithelial breast cancer cell lines (MDA-MB-231, MDA-MB-436, and MDA-MB-468), which are classified as the most aggressive subtypes known as triple-negative breast cancer." (PMID 39479021, 2024). "The increment of miR-155-5p levels was observed in breast cancer cell lines, and targeting of mir-155-5p by NORAD positively regulated the tumour suppressor protein SOCS1, showing ameliorative effects in vitro." (PMID 40176927, 2024). "Here, we demonstrate that downregulation of NORAD sensitizes human breast cancer cells to doxorubicin." (PMID 37680988, 2023). "lncRNA-NORAD expression is significantly inhibited by NORAD upon migration and invasion of breast cancer cell lines." (PMID 37256184, 2023). "Characterization of breast cancer cells was performed 48 h after NORAD downregulation, the time at which we detected lower NORAD levels." (PMID 37680988, 2023). "In this study, we reported that NORAD is overexpressed in breast cancer, conferring resistance to chemotherapy, and interfering with γH2AX signaling upon DNA damage." (PMID 37680988, 2023). "Our results support this scenario where higher NORAD levels are associated with an aggressive breast cancer subtype (TNBC) and poor relapse-free survival of patients, while NORAD KD inhibits cancer cell viability and migration." (PMID 37680988, 2023). "In summary, we demonstrated that NORAD confers resistance of breast cancer cells to a chemotherapeutic agent." (PMID 37680988, 2023). "We observed a reduction in doxorubicin IC50 upon NORAD KD through alamarBlue cellular viability assay (IC50 shifted from 0.3779 to 0.05680 μM), indicating that NORAD KD sensitizes breast cancer cells to chemotherapy." (PMID 37680988, 2023). "In the present study, we confirmed upregulated NORAD expression levels in a set of human epithelial breast cancer cell lines (MDA-MB-231, MDA-MB-436, and MDA-MB-468), which belong to the most aggressive subtypes (triple-negative breast cancer)." (PMID 37680988, 2023). "Recent studies indicated that NORAD was highly expressed in numerous human cancers, including breast cancer, esophageal squamous cell carcinoma, pancreatic cancer, colorectal cancer, bladder cancer, and cervical cancer, with poor overall survival." (PMID 36514044, 2022). "This work makes RALGABP a new player in genomic instability promoted by NORAD dysregulation in breast cancer." (PMID 36412911, 2022). "The functional effect of NORAD in activation of TGF-β signaling has also verified in breast cancer cells." (PMID 34485302, 2021).
breast carcinoma (continued). "In another study, it was proposed that NORAD is downregulated in lung and breast cancer and that the overexpression of NORAD impedes metastasis in vivo." (PMID 34298879, 2021). "Further studies in malignant melanoma, cervical cancer, breast cancer and lung cancer supported oncogenic effects of NORAD in xenograft models." (PMID 34485302, 2021). "In contrast, NORAD serves as a suppressor gene in neuroblastoma and breast cancer, respectively, which is consistent with our results." (PMID 35047491, 2021). "Recently, it has been demonstrated that histone deacetylation and nucleosome occupancy by YAP, TAZ, TEAD, and NuRD complex, are responsible for NORAD expression regulation in breast cancer cell lineage." (PMID 33739352, 2021). "For example, lncRNA APOC1P1–3 has been found to inhibit breast cancer cell apoptosis by decreasing α-tubulin acetylation; lncRNA NORAD has been reported to suppress breast cancer metastasis by sequestering S100P." (PMID 32943090, 2020). "This suggests that the oncogenic activity of lnc-NORAD is at least through activating TGF-β signaling pathway for the progression of breast cancer in the advanced stages." (PMID 30930692, 2019). "Our study has identified that overexpression of lnc-NORAD is constitutively related to the TGF-β signaling pathway in breast cancer." (PMID 30930692, 2019). "In the present study, high lnc-NORAD expression in both breast cancer cell lines and patient tumors was confirmed, and worse prognosis was observed in the high lnc-NORAD expression group." (PMID 30930692, 2019). "In order to uncover the mechanisms of lnc-NORAD promote the development of breast cancer, we analyzed lnc-NORAD impact on TGF-β by western blot." (PMID 30930692, 2019). "In breast cancer, NORAD knockout significantly suppressed tumor cell growth and proliferation, suggesting that it plays an oncogenic role." (PMID 29121972, 2017). "In breast cancer, cellular levels of NORAD were downregulated compared to the control." (PMID 40176927, 2024). "NORAD expression has been observed in various cancers, including breast cancer." (PMID 39479021, 2024). "Initially, we determined the basal mRNA levels of NORAD in a set of human breast cancer cell lines (MCF-7, MDA-MB-231, -436, and -468) and in a non-malignant human mammary epithelial cell line (MCF-10A) by real-time quantitative reverse transcriptase polymerase chain reaction (qRT-PCR)." (PMID 37680988, 2023). "Importantly, lncRNA NORAD is overexpressed in many cancers, including breast cancer, gastric cancer, bladder cancer, liver cancer, and so on." (PMID 35645836, 2022). "NORAD also serves as a platform for S100P binding, suppressing lung and breast cancer metastasis." (PMID 33739352, 2021). "Therefore, we identify that lncRNA-NORAD acts as an oncogenic RNA in the breast cancer tumorigenesis and the lnc-NORAD/TGF-β/RUNX2 axis in the breast cancer tumorigenesis." (PMID 30930692, 2019). "Bernardes de Jesus and colleagues uncover how NORAD downregulation sensitizes triple-negative breast cancer cells to chemotherapy, through an impaired DNA damage response, highlighting how NORAD may represent an unexploited therapeutic target for breast cancer." (PMID 37680988, 2023). "Therefore, our findings suggest that high expression of NORAD may be indicative of a more aggressive form of breast cancer." (PMID 37680988, 2023). "According to KEGG analysis, NORAD is predominantly enriched in hepatitis B, the RAGE signalling pathway in diabetes complications, Proteoglycans in cancer, breast cancer and cellular senescence." (PMID 37993524, 2023). "In breast cancer, lncRNA-NORAD expression is downregulated, and the Hippo signaling pathway and the YAP/TAZ–TEAD complexes result in the suppression of NORAD transcription, which in turn promotes tumor metastasis and invasion." (PMID 37256184, 2023).
breast carcinoma (continued). "Among these five lncRNAs, the XIST (p = 9.2e−12), NORAD (p = 1.1e−9), and OIP5-AS1 lncRNAs (p = 8.3e−11) were expressed differentially in breast cancer." (PMID 36312586, 2022). "MIR29B2CHG, NEAT1, MALAT1, AC005332.4, NORAD, and XIST were elevated in normal breast samples than in breast cancer samples." (PMID 35756601, 2022). "Our findings indicate that NORAD and HCG11 are differentially expressed in breast cancer subtypes and participate in distinct regulatory networks." (PMID 33739352, 2021). "The role of NORAD in activation of TGF-β has been verified in different cancers, namely hepatocellular carcinoma, breast cancer and lung cancer." (PMID 34485302, 2021). "Considering all breast cancer subtypes as a group, NORAD levels do not correlate with relapse-free survival (n = 2032, p = 0.057) nor overall survival (n = 943, p = 0.25)." (PMID 37680988, 2023). "We performed Kaplan–Meier and Cox proportional hazards regression analyses to verify if the signatures of NORAD and RALGAPB could predict the overall survival (OS) in breast cancer patients." (PMID 36412911, 2022). "Expression levels of MAPK14 and NORAD were not significantly different between breast cancer tissues and ANCTs." (PMID 32433496, 2020). "However, there is currently a lack of studies investigating NORAD expression in the peripheral blood of breast cancer (BRCA) patients." (PMID 37993524, 2023). "However, expression levels of MAPK14 and NORAD were not significantly different between breast cancer tissues and ANCTs." (PMID 32433496, 2020). "Here we investigated the expression profile of NORAD and HCG11 in tumor and non-tumor breast tissue RNA-seq datasets from TCGA, focusing on each breast cancer subtype and also in tumor samples from Brazilian patients." (PMID 33739352, 2021). "Finally, we selected four lncRNAs with higher predicted scores (NORAD, HCG11, ZNRD1ASP and TTN-AS1) and assessed their expression in 80 breast cancer tissues and their adjacent non-cancerous tissues (ANCTs)." (PMID 32433496, 2020).
colorectal cancer (18 papers, 2020 to 2024). A primary or metastatic malignant neoplasm that affects the colon or rectum. "The ROC curve analysis confirmed the potential of NORAD as a diagnostic biomarker for colorectal cancer." (PMID 37993524, 2023). "And high NORAD expression was associated with tumor progression in colorectal cancer." (PMID 32694945, 2020). "Further systematic investigation is required to thoroughly understand the dual roles of NORAD and to clarify the molecular mechanisms both upstream and downstream of NORAD, in order to gain insight into its potential role in colorectal cancer." (PMID 38791575, 2024). "For instance, NORAD promotes colorectal cancer stem-like cell invasion by functioning as a miR-203a sponge." (PMID 34969360, 2022). "An inverse relationship between NORAD and miR-202-5p expression was found to play a pivotal role for colorectal cancer progression, expressed by NORAD dependent downregulation of miR-202 expression in CRC tissues and xenografted cell lines." (PMID 35682549, 2022). "A single study in patients with colorectal cancer demonstrated down-regulation of NORAD in tumor tissues particularly in samples obtained from patients developed distant metastasis." (PMID 34485302, 2021). "has shed light on the promotive effects of NORAD overexpression on colorectal cancer cell proliferation, migration, and invasion." (PMID 34551785, 2021). "Another research revealed that NORAD was upregulated in colorectal cancer tissues, and NORAD inhibition induced apoptosis and constrained invasion, migration, and proliferation of colorectal cancer cells." (PMID 32694945, 2020). "High NORAD expression in colorectal cancer is related to the advanced tumor stage." (PMID 36726840, 2023). "NORAD also contributes to tumor growth in colorectal cancer as a ceRNA of miR-202-5p." (PMID 35281474, 2022). "Importantly, NORAD can promote the progression of hepatocellular carcinoma, colorectal cancer, non-small cell lung cancer, and malignant melanoma by targeting different miRNAs." (PMID 33722248, 2021). "Moreover, NORAD boosts colorectal cancer cell proliferation, migration, and invasion by means of inhibiting microRNA-202-5p (miR-202-5p) expression." (PMID 34551785, 2021). "However, two other studies in colorectal cancer cells reported the role of NORAD in increasing cell viability, proliferation, migration and invasion while inhibiting apoptosis." (PMID 34485302, 2021). "In addition, lncRNA NORAD has been reported that contributes to colorectal cancer progression by inhibition of miR-202-5p." (PMID 33269379, 2021). "A single study in colorectal cancer cells showed down-regulation of NORAD." (PMID 34485302, 2021). "NORAD knockdown also induces colorectal cancer cell apoptosis through the NORAD/miR-202-5p axis." (PMID 32267831, 2020). "For example, NORAD could promote the development of ovarian cancer, gastric cancer, and pancreatic cancer colorectal cancer." (PMID 32267831, 2020). "The literature reports several oncogenic lncRNAs associated with tumor proliferation, metastasis and poor prognosis in colorectal cancer, such as PVT1, NORAD, CCAT1, CCAT2 and CRNDE." (PMID 38791575, 2024).
gastric cancer (14 papers, 2020 to 2024). A primary or metastatic malignant neoplasm involving the stomach. "As evidence, NORAD has been linked to oxaliplatin resistance in gastric cancer by enhancing autophagy levels." (PMID 36983973, 2023). "Within CAFs, elevated expression of NORAD augments the release of IL-33 to gastric cancer cells, thereby stimulating their proliferative activity." (PMID 39717771, 2024). "To date, research on the role of lncRNA NORAD in various diseases has primarily focused on its impact on different types of cancer, including ovarian cancer, gastric cancer, pancreatic cancer, and colorectal cancer." (PMID 39215037, 2024). "Consistently, it was recently found that NORAD aggravated cell growth, mobility, and invasiveness in renal cancer and gastric cancer." (PMID 36245705, 2022). "After treated with 2 μg/mL oxaliplatin, the expression of NORAD is significantly enhanced in gastric cancer cells." (PMID 33462197, 2021). "In 379 gastric cancer patients, we found that NORAD expressed higher in gastric cancer patients compared with adjacent normal gastric tissues; and miR-433-3p expressed lower in gastric cancer tissues." (PMID 33462197, 2021). "Upregulation of NORAD promoted gastric cancer progression by activating the RhoA/ROCK1 axis, which correlated with poorer prognosis." (PMID 33292272, 2020). "NORAD promotes gastric cancer cell proliferation and migration by regulating the miR-608/FOXO6 pathway." (PMID 32267831, 2020). "miR-433-3p expression was increased in NORAD knockdown gastric cancer cells." (PMID 33462197, 2021). "This strongly suggested that autophagy is involved in oxaliplatin resistance in gastric cancer and inhibiting autophagy by targeting NORAD may be a potential strategy to reverse the oxaliplatin-resistant status of SGC-7901-R cells." (PMID 33462197, 2021). "NORAD was discovered as an oncogene in bladder cancer, osteosarcoma and gastric cancer." (PMID 31894841, 2020). "Downregulation of NORAD promotes the production of apoptosis-related proteins by increasing PARP, caspase-3, and Bax and inhibits the proliferation and invasion of gastric cancer cells." (PMID 37517088, 2023). "We found that NORAD was highly expressed in gastric cancer cell lines compared to normal gastric epithelium cell line, GES-1, and that NORAD expression was higher in oxaliplatin-resistant cells than their parental cells." (PMID 33462197, 2021). "Moreover, NORAD and miR-433-3p differentially expressed between recurrent and nonrecurrent gastric cancer patients." (PMID 33462197, 2021). "NORAD then sponges miR-433-3p to increase the expression of autophagy-related genes ATG5 and ATG12, which helps in alleviating DNA damage and oxidative stress and eventually confers oxaliplatin resistance in gastric cancer (GC) cells." (PMID 35625948, 2022).
lung cancer (14 papers, 2019 to 2024). A malignant neoplasm involving the lung. "NORAD has been reported to be highly expressed in lung tissues and is associated with tumorigenesis and progresses of lung cancer." (PMID 35480402, 2022). "For example, Tian9 reported that NORAD is upregulated in both hepatocellular carcinoma tissues and cells, and it has been revealed that NORAD expression levels were also increased in lung cancer tissues and cells." (PMID 37993524, 2023). "In vivo studies in xenograft models of ovarian, cervical, breast, gastric, colorectal, liver and lung cancers as well as neuroblastoma and osteosarcoma have shown the efficacy of NORAD-targeting therapeutic options in reducing tumor burden." (PMID 34485302, 2021). "In lung cancer cells, NORAD promotes EMT-like characteristics through activation of TGF-β signaling." (PMID 34485302, 2021). "The lncRNA NORAD regulates lung cancer cell proliferation, apoptosis, migration and invasion via the miR‐30a‐5p/ADAM19 axis." (PMID 32569434, 2020). "Additionally, NORAD promotes lung cancer cell proliferation by sponging miR-136-5p." (PMID 34258296, 2021).